SNORD58 (Small nucleolar RNA SNORD58 )
Synonyms: LOC124903416
Gene: Small nucleolar RNA gene on chromosome 14 (45,088,243 to 45,088,308, forward strand). Ensembl gene ENSG00000212615.
Gene Ontology:
Biological process: RNA processing
Cellular component: nucleolus
Homologues: Orthologues: chimpanzee SNORD58 (100% identical), tropical clawed frog SNORD58 (70% identical). Paralogues in human: SNORD58B (91% identical), SNORD58A (71% identical), SNORD58C (70% identical).
Diseases named in the same sentence as SNORD58 in open-access papers:
SNORD58 is named in the same sentence as 2 diseases in open-access papers, as found by Europe PMC text mining. Sharing a sentence is not in itself a finding about the gene and the disease.
SNORD58 shares sentences with these, for which no sentence is quoted: osteoarthritis (1 paper); viral infections (1).